FGF1 (fibroblast growth factor 1)
Diseases named in the same sentence as FGF1 in open-access papers (continued):
Sharing a sentence is not in itself a finding about the gene and the disease.
tumor (continued). "RT‐qPCR analysis demonstrated that, of nine TRmRNAs, DPEP1, FGF1 and MPP7 were largely expressed in normal tissues, whereas the other six mRNAs exhibited elevated expression levels in tumour tissues." (PMID 40673609, 2025). "VEGFC, FGF1, INHBA, FYN, and AGTR1 promote angiogenesis, lymphangiogenesis, EMT, invasion, and tumor cell survival – constituting pro-metastatic signaling." (PMID 41006647, 2025). "FGF1 and FGF2 mutants defective in integrin binding were defective in signaling, whereas the mutants still bound to FGFR suppressed angiogenesis and tumor growth, indicating that they act as antagonists." (PMID 38391921, 2024). "Western blot analysis illustrated that LY2874455 treatment restrained FGF1, FGF2, STAT1, and LDHA levels but increased LDHB levels in tumor tissues." (PMID 38764020, 2024). "Using these data, we analyzed responses to AZD4547 based on the mRNA expression of FGFs (FGF1–23) and FGFRs (FGFR1–4) in EOC patient tumor samples to test for the possible role of these genes as predictive biomarkers for AZD4547." (PMID 38273381, 2024). "When EC patients were classified based on tumor grade, significant elevation in the levels of angiopoietin-2 (p = 0.015), FAP (p = 0.033), FGF-1 (p = 0.0004), and VEGF-A (p = 0.018) were observed in the more advanced grade 3 tumors compared to grade 1 tumors." (PMID 39511039, 2024). "The expression of FGF1 and FGF2 correlated inversely with tumor size and the Nottingham Prognostic Index (p = 0.03 and p = 0.002, respectively)." (PMID 39302921, 2024). "The downregulation of FGF-1 was shown in tumorous tissues, and the expression of VEGFR-1, -2, and -3 receptors was also detected both in tumorous and adjacent healthy tissues of RCC." (PMID 39062015, 2024). "Conventional FGF1 and unconventional FGF2 interact with FGFR3 and FGFR1 on tumours, respectively, which promotes the enhancement of tumour cell invasion mediated by CAFs." (PMID 40135140, 2024). "It has been demonstrated that FGF1 is elevated in CRC tissues and induces the invasion and metastasis of tumor cells." (PMID 38201598, 2023). "The stronger protective effect of FGF1 than EGF against taltobulin and its effect on MCF-7 cell migration suggests its particular relevance in tumor progression and drug resistance." (PMID 37509496, 2023). "A further paracrine loop between CAF-derived FGF1 and cancer cell MYC activation has also been identified, with FGFR inhibition showing reduced MYC levels and tumour size, particularly when combined with MEK inhibition." (PMID 36357571, 2023). "Integrin αvβ3 mediates EMT induction by several factors, such as transforming growth factor-beta 1 (TGF-β1), pituitary tumor transforming gene (PTTG), and fibroblast growth factor 1 (FGF1)." (PMID 35682554, 2022). "When upregulated in tumor ECs treated with HLSC-EVs, miR-181b suppressed the expression of the pro-angiogenic genes fibroblast growth factor 1 (FGF1) and urokinase-type plasminogen activator (uPA)." (PMID 35626707, 2022). "Our bioinformatic analysis showed that tumor angiogenesis-related proteins, including EGFR, FGF1, FGF2, VEGRR2, and PDGFRA, were in the top 15 key targets in the PPI network of QDSJ decoction treating NF2-associated VS." (PMID 36059985, 2022). "While most of its physiological functions are shared with FGF1, FGF2 plays a vital role in tumor-induced angiogenesis, contributing to tumor growth." (PMID 35784465, 2022). "In primary tumors, tumor cells produced VEGF and fibroblast growth factor 1 (FGF1) to increase vascular density." (PMID 35454769, 2022). "FGF1 is an essential pro-angiogenic factor involved in tumor angiogenesis in a VEGF-independent manner; uPA is critical for tumor angiogenesis and progression by participating in the proteolytic processes of extracellular matrix degradation." (PMID 35626707, 2022).
tumor (continued). "The results demonstrate that the expression of EGFR, IGF1, PTGS2, FGF1, CAV1, and PLCB1 were significantly different (p < 0.01) in PABC tissues as compared to non-tumor tissues, with a similar pattern to that observed in the microarray analysis." (PMID 36035177, 2022). "The experimental results showed that the levels of FGF1, TGF‐β and Ang‐4 decreased, whereas the levels of ERK1/2 and Akt phosphorylation increased in HCT116 tumour tissue following combined treatment with both drugs." (PMID 35701366, 2022). "FGF1 and FGF2 appear to have the greatest roles in cancer as both of them can act as tumor growth factors and thus increase tumor growth and invasion." (PMID 33799622, 2021). "FGF1 and FGF2 are correlated with increased sinusoidal capillarization, which is involved in tumor angiogenesis." (PMID 33935756, 2021). "Members of FGF family (including FGF1, FGF2, FGF4, FGF5, FGF6, FGF7, and FGF9) were reported to be secreted by CAFs and FGFR2 was shown to be a key mediator of tumor niche-derived signals that are responsible for the acquisition of tamoxifen resistance." (PMID 34830951, 2021). "In detail, FGF1 and FGF10 were downregulated in most of the tumor types whereas FGF3, FGF5, FGF11, FGF19, FGF20, and FGF21 were upregulated in most of the tumor types." (PMID 32596330, 2020). "Of note, the weight gain and the adipocyte diameter positively correlated with (i) the levels of FGF1, (ii) FGFR1 activation in tumor cells, and (iii) estrogen-independent tumor growth." (PMID 33081025, 2020). "The results revealed that YAP1 is directly connected to secreted AREG, CTGF, CYR61, FGF1 and MSLN that are involved in fibrosis and other key signaling pathways involved in the tumor-stroma interactions." (PMID 32054505, 2020). "S100A13 can act on the regulation of FGF-1 and participate in the regulation of VEGF-A, which is related to tumor grading and promotes tumor to be more invasive and aggressive." (PMID 33046974, 2020). "As a consequence of these changes in rRNA methylation, the translation of messages with IRESs is increased; such as those with products that promote tumor development (IGF-1R, c-myc, VEGF-A and FGF1)." (PMID 28808137, 2017). "M2-like TAMs are characterized by a constitutive high expression of multiple tumor growth promoting factors, including VEGF, FGF1 and 2, PDGF, GM-CSF, insulin-like growth factor-1, and TGF-β." (PMID 28670313, 2017). "We further demonstrated the anti-angiogenic capacity of quininib by examining gene expression of angiogenic factors in xenograft tumours and found that the expression of IL6, IL8, NRP2, VEGFA and FGF1 was reduced by quininib treatment." (PMID 27739445, 2016). "The fibroblast growth factors FGF-1 and FGF-2 are heparan sulfate (HS)-binding proteins that play key roles in tumor angiogenesis, a critically important process in tumor growth and development." (PMID 22895025, 2012). "Secondly, LLL12 reduced tumor-associated angiogenic factors (VEGF, MMP-9, angiopoetin, TF and FGF1), probably as a direct consequence of STAT3 inhibition in tumor cells." (PMID 22530037, 2012). "In the case of the FGF-1 tumours, however, overall tumour hypoxia was unchanged despite a significant (although less pronounced than in the VEGF121 tumours) decrease in perfused vessel spacing." (PMID 14735189, 2004). "Distinguished from FGF1, FGF7 may primarily act in synergy with progesterone to escalate tumor development and metastasis." (PMID 40826783, 2025). "iCCA cells secrete FGF1, which activates FGFR2 signaling to sustain tumor growth." (PMID 41430037, 2025). "Additionally, copper ions contributed to tumor angiogenesis by activating many angiogenic factors, such as vascular endothelial growth factor (VEGF), VEGF2, and fibroblast growth factor 1 (FGF1)." (PMID 38696071, 2024).
tumor (continued). "Based on the Spearman correlation analysis in GEPIA, we identified a significant correlation between STAT1 and LDHA/LDHB/FGF1/FGF2 in tumor tissues but not in normal tissues." (PMID 38764020, 2024). "There is a closely regulatory relationship between fibroblast growth factor 1 (FGF1) and the mTOR-S6K1 pathway, which may promote tumor cell proliferation and metastasis by regulating the AKT mTOR-S6K1 signaling pathway in various tumors." (PMID 37964239, 2023). "KYNA is also considered a tumor suppressor due to the inhibition of fibroblast growth factor-1 (FGF-1) release, which is involved in MMPs activation, angiogenesis, tumor progression, promotion of cancer cells stemness and is associated with worst patients’ prognosis." (PMID 34071442, 2021). "Depletion of FGF1 alleviated the nutritional status of mice to a certain extent, and significantly inhibited the proliferative capacity of the CRC cells, which was manifested as reduced tumor size and weight compared to control group." (PMID 34552869, 2021). "Then, we evaluated the difference of mice weight after tumor removal, and the weight of mice in FGF1-KD group was still superior to negative controls." (PMID 34552869, 2021). "To take a further step to clarify the effects of PAM in tumor microenvironments, we also investigated whether PAM affects the secretion of FGF-1 and TGF-β1." (PMID 33097755, 2020). "Furthermore, cluster analysis indicated that both FGF1 and AKR1B10 expression levels were able to distinguish between the tumor and adjacent normal tissues, and pointed to a functional relationship as well." (PMID 32615540, 2020). "Indeed, AKRB110 inhibited FGF1 in CRC cell lines, and elevated FGF1 in response to AKR1B10 depletion promoted xenograft tumor growth in a mouse model." (PMID 32615540, 2020). "Upregulated expression of various canonical FGFs (including FGF1, FGF2, and FGF 6–9) derived from tumor cells or stromal cells induces tumor progression in various cancers; however, the effects of circulating hormone-like FGFs (such as FGF19, FGF21, and FGF23) on tumors are unclear." (PMID 31408968, 2019). "The specific stem cell markers ALDH1A (in keeping with the IHC result), ABCG2, and FGF1 were consistently and significantly over-expressed (all p values < 0.05) in the invasive margin of GBM when compared to rim and core tumour regions from where samples are conventionally taken." (PMID 29156557, 2017). "In support of this possibility we found that, unlike FGF2, effects of the acidic FGF1 (pI≈6) on tumour cell proliferation were not affected by α3(V) ablation and that FGF1 did not bind α3(V)-NTD or GPC1 in immunoprecipitations." (PMID 28102194, 2017). "The expression of tumour cell-produced pro-angiogenic ligands was examined using human-specific primers on day 28 after tumour cell (Y-MESO-14) inoculation, and the upregulation of VEGFA and FGF1 was observed." (PMID 26635184, 2015). "Whereas non-SP cells formed fewer and slower-growing tumours, SP cells over-expressed many genes associated with cancer stem cell and drug resistance: ABCG2, FGF1, IGF1, MYC, SOX1/2, WNT1, as well as genes involved in angiogenesis, Notch and Hedgehog pathways." (PMID 20424609, 2010). "The expression of endogenous murine VEGF-C, VEGF-D, and FGF-1 in total tumors and tumor cells (not considering the high levels of transgenic human VEGF-C expression in RT2;VC mice) was higher than in TAM." (PMID 19759906, 2009). "Fibroblast growth factor 1 (FGF1) is a growth factor for both tumour and stromal (endothelial) cells and induces the expression of matrix metalloproteinases (MMPs) and angiogenesis in cancer, hence its involvement in tumour progression." (PMID 17242701, 2007).
tumor (continued). "FGF1 and FGF2 belong to the FGF family, which possesses broad mitogenic and cell survival activities, and are involved in a variety of biological processes, including embryonic development, cell growth, morphogenesis, tissue repair, and tumour growth and invasion." (PMID 39940657, 2025). "On the other hand, in our study we observed that the expression of upstream signaling molecules such as VEGFA and FGF1 was also regulated by KDM6B, which may form a positive feedback loop, strengthening the inhibition of tumor progression after targeted blockade of KDM6B." (PMID 33664867, 2021). "Furthermore, FGF1 promotes tumor-niche fibroblasts to express and secrete HGF (hepatocyte growth factor), a mediator of angiogenesis and cell motility, and an important tumor-resistant factor in melanomas." (PMID 34830951, 2021). "Interestingly, a 40-kDa form of SYT1 participates in the non-classical export of FGF1, a protein that regulates many cellular processes including angiogenesis, morphogenesis and tumor growth suggesting a potentially key role of SYT1 in cancer." (PMID 24505276, 2014). "Indeed, the absence of IL-1β in the tumor microenvironment limited the recruitment of FGF1-producing mononuclear cells to tumor sites." (PMID 24734023, 2014). "In CRLM patients, NRAS, FGF1, and KDR mRNA and protein were expressed at higher levels in metastatic than in CRC primary tumor and adjacent noncancerous tissue (p < 0.05)." (PMID 38201598, 2023). "AHNAK2 is needed for the non-classical secretion of FGF1 that can bind to fibroblast growth factor receptors (FGFR), exerting an effect on cell growth, tissue repair, tumour growth, invasion, and various cell survival related activities." (PMID 35158796, 2022). "Administration of exogenous FGF1, but not EGF, reduced the inhibitory effect on ERK1/2 activation by MEK inhibitors and reduced the inhibition of tumor growth by the ER antagonist ICI 182780 in MCF-7 cells." (PMID 34830951, 2021). "The expression of FGF1 and FGF2 is induced in chronic liver diseases, and their expression levels are increased in more advanced tumor stages." (PMID 33935756, 2021). "Fibroblast growth factor 1 (FGF1) is a growth factor of the nonclassical release pathway and plays an important role in regulating the MAPK-ERK signaling pathway, cell growth, tumor invasion, and angiogenesis." (PMID 32904605, 2020). "Interestingly, the switch in the expression levels of FGF1 and FGF2 (downregulated and upregulated in low-responder cells, respectively) as well as the upregulation of one member of the PDGF family (i.e. PDGFD) might be potentially driving the tumor progression in these GBM low-responder cells." (PMID 34316686, 2020).
cancer (117 papers, 1995 to 2026). A tumor composed of atypical neoplastic, often pleomorphic cells that invade other tissues. "Mechanistically, FAK inhibition has been shown to reprogram cancer-associated fibroblasts (CAFs), suppressing the production of fibroblast growth factor-1 (FGF1), a driver of resistance to RAF-MEK inhibition." (PMID 39976799, 2025). "Study has shown that if certain signal mutations cause the destruction of FGF1, it is likely to give rise to cancer." (PMID 36925653, 2023). "FGF1 association with various cancer types indicates its potential diagnostic and therapeutic importance." (PMID 37108717, 2023). "Based on the largely improved affinity for FGFR1 and the simplicity of preparation we selected the tetrameric variant of FGF1-SA as a basis for development of selective cytotoxic conjugates targeting cancer cells overproducing FGFR1." (PMID 34635096, 2021). "For example, overexpression of FGF2 and FGF1 are linked with both in vivo and in vitro resistance to cancer drugs such as doxorubicin, 5-fluorouracil and paclitaxel." (PMID 34830836, 2021). "Many FGFs and their elevated levels are associated with cancer progression, for example FGF1, -2, -6, -8, -10, -19 and -23." (PMID 34830836, 2021). "Consistent with the GEPIA online analysis, the result of qRT-PCR which was conducted using 30 local hospital ccRCC and paired normal renal tissues also supported the FGF1 loss of expression in cancer." (PMID 33865387, 2021). "The blockage of the FGF-1 signaling pathway causes a cell cycle arrest in phase G0/G1, thus decreased cancer cell proliferation." (PMID 34071442, 2021). "Furthermore, we found that importin α1 at the cell surface is associated with a growth factor, FGF1, thereby enhancing its signalling pathway and accelerating the proliferation of cancer cells." (PMID 26887791, 2016). "Furthermore, FGF1 is implicated in cancer initiation and progression." (PMID 41430037, 2025). "Thus, it is possible that the mitogenic function of FGF1 can be reduced by a natural product, combination therapy including a natural product with FGF1 might be able to facilitate the clinical application of FGF1 while minimizing the risk of cancer." (PMID 36110535, 2022). "On one hand, PGE2 acts on cancer cells to induce their secretion of fibroblast growth factor 1 (FGF1), which subsequently stimulates CAF proliferation and enhances their fibrotic activity." (PMID 40948749, 2025). "To make a vector suitable for targeting cancer cells overexpressingFGFRs, we generated an engineered version of the FGF1 protein, a naturalligand for all four human FGFRs (FGFR1-4)." (PMID 39989790, 2025). "Eighteen overlapping DEGs were identified between the two CRC cell lines, four of which are closely related to cancer progression, namely FGF1, THBS2, DAPK2, and GSTM2." (PMID 41039172, 2025). "LRRC59 promotes cancer progression by regulating the nuclear transport of exogenous FGF1, and accelerates cancer cells proliferation and metastasis in various cancers." (PMID 38738999, 2024). "Further, reduced sensitivity to tamoxifen (an estrogen blocker) was observed in vitro in the michigan cancer foundation—1 cells (MCF7) with FGF1." (PMID 38635549, 2024). "As the effect of FGF1-PIGN on cancer cells was only investigated in ISOS-1 cells, further analysis using other cancer cells, such as PANC-1 cells, is necessary." (PMID 38637316, 2024). "We revealed that both honokiol and FGF ligand trap prevent FGF1-dependent protection against taltobulin in cancer cells expressing FGFR1." (PMID 39329123, 2024). "Patients with low-to-moderate grade carcinoma had significantly higher expression of FGF1 and FGF2 compared to their counterparts with high-grade tumors." (PMID 39302921, 2024). "Together with our results in the present study, these findings indicate that FGF1 is a potential therapeutic target for treatment of DOX-induced hepatotoxicity in cancer patients." (PMID 37999577, 2023).